CGRRF1 (cell growth regulator with ring finger domain 1)
Description:
Able to inhibit growth in several cell lines.
Synonyms: CGR19; RNF197
Tractability: PROTAC: ubiquitination databases record sites on it.
Gene: Protein-coding gene on chromosome 14 (54,509,812 to 54,539,292, forward strand). Ensembl gene ENSG00000100532.
Subcellular location: Nucleus; Endoplasmic reticulum
Subcellular location (Human Protein Atlas): Nucleoplasm; Vesicles
Gene Ontology:
Molecular function: protein binding
Biological process: negative regulation of cell growth; negative regulation of cell population proliferation
Cellular component: endoplasmic reticulum; nucleoplasm; nucleus
Genetic constraint (gnomAD): Loss-of-function variants: 18 observed, 24.33 expected, observed/expected ratio (o/e) 0.74, 90% interval 0.51 to 1.1. The upper end of that interval is the gene's LOEUF score, 1.1, which puts it in group 4 of 6, group 1 being the genes least tolerant of losing a copy. Missense variants: 285 observed, 291.81 expected, observed/expected ratio (o/e) 0.98, 90% interval 0.89 to 1.08. Synonymous variants: 109 observed, 113.18 expected, observed/expected ratio (o/e) 0.96, 90% interval 0.82 to 1.13.
Homologues: Orthologues: chimpanzee CGRRF1 (99% identical), macaque CGRRF1 (99% identical), dog CGRRF1 (94% identical), pig CGRRF1 (94% identical), rabbit CGRRF1 (94% identical), guinea pig CGRRF1 (91% identical), rat Cgrrf1 (84% identical), mouse Cgrrf1 (84% identical), tropical clawed frog cgrrf1 (67% identical), zebrafish cgrrf1 (48% identical).
Diseases named in the same sentence as CGRRF1 in open-access papers:
CGRRF1 is named in the same sentence as 14 diseases in open-access papers, as found by Europe PMC text mining. Sharing a sentence is not in itself a finding about the gene and the disease. The quoted sentences say what the papers report.
endometrial cancer (2 papers, 2018 to 2019). Primary or metastatic malignant neoplasm involving the endometrium (mucous membrane that lines the endometrial cavity). "In endometrial cancer cell lines, overexpression of CGRRF1 suppresses cell proliferation and knockdown of CGRRF1 enhances cell growth." (PMID 31801577, 2019). "CGRRF1 expression is reduced in colon and endometrial cancer (Fig EV5G; TCGA, 2012), which correlates with increased Evi protein levels and a lack of transcriptional upregulation of Evi as assessed by TCGA expression data (Fig EV5H; TCGA, 2012)." (PMID 29378775, 2018).
breast carcinoma (1 paper, 2019). "Publicly available breast cancer datasets were analyzed to examine the association between CGRRF1 and breast cancer." (PMID 31801577, 2019). "Basal-like breast cancer patients have the worst survival, so the association of low CGRRF1 with poor survival could be in part due to the fact that some cancers with low CGRRF1 expression are basal-like subtype." (PMID 31801577, 2019). "Its downregulation is associated with CGRRF1 promoter hypermethylation in breast cancer." (PMID 31801577, 2019). "To understand whether the decrease in CGRRF1 in breast carcinoma is caused by alterations in epigenetic modifications, we examined the methylation status of the promoter of CGRRF1 in the TCGA breast cancer cohort." (PMID 31801577, 2019). "We further noticed that CGRRF1 promoter methylation is increased in breast cancer as compared to that in normal breast tissue, suggesting that CGRRF1 is epigenetically modified in breast cancer." (PMID 31801577, 2019). "We show that CGRRF1 inhibits the growth of breast cancer in vitro and in vivo, and the RING-finger domain is important for its growth-inhibitory activity." (PMID 31801577, 2019). "We demonstrated a tumor-suppressive function of CGRRF1 in breast cancer and identified EGFR as its target." (PMID 31801577, 2019). "CGRRF1 expression is lower in breast carcinoma as compared to normal breast tissue, and patients with lower CGRRF1 expression in their tumors have a worse outcome." (PMID 31801577, 2019). "We do not see this association in the basal-like cohort, probably because most basal-like breast cancers already express low levels of CGRRF1." (PMID 31801577, 2019). "By analyzing the breast cancer database, we found that patients with low CGRRF1 expression have shorter survival." (PMID 31801577, 2019). "We further analyzed the correlation between CGRRF1 transcript levels and its promoter methylation status in the TCGA breast cancer cohort." (PMID 31801577, 2019). "Comparing the transcript levels of CGRRF1 between matched normal breast tissues and breast tumors in the TCGA breast cancer cohort, we noticed that CGRRF1 expression is significantly lower in tumor tissues." (PMID 31801577, 2019). "The expression of CGRRF1 is decreased in cancer tissues; however, the role of CGRRF1 in breast cancer and the mechanism(s) of its growth suppressor function remain to be elucidated." (PMID 31801577, 2019). "Treatment of 5-azactidine and panobinostat restored CGRRF1 expression, supporting that the promoter of CGRRF1 is epigenetically modified in breast cancer." (PMID 31801577, 2019). "In the TCGA breast cancer cohort, both HER2-positive and basal-like breast cancer patients had significantly lower expression of CGRRF1 compared to other subtypes." (PMID 31801577, 2019). "We demonstrate that CGRRF1 suppresses growth of breast cancer and its E3 ligase activity is involved in CGRRF1-mediated growth suppression." (PMID 31801577, 2019). "To test the epigenetic mechanism for downregulation of CGRRF1 in breast cancer, we treated a panel of breast cancer cell lines with a demethylation agent, 5-azactidine." (PMID 31801577, 2019). "Together, these results indicated that epigenetic alterations in the CGRRF1 promoter lead to its downregulation in breast cancer." (PMID 31801577, 2019). "We found that lower expression of CGRRF1 is also associated with a shorter patient overall survival in the Luminal A subtype and HER2-positive subtype of breast cancer." (PMID 31801577, 2019). "The expression of CGRRF1 is downregulated in breast carcinoma, and breast cancer patients with lower CGRRF1 had poor survival." (PMID 31801577, 2019). "In this study, we demonstrate the in vitro and in vivo growth-inhibitory activity of an ER-resident E3 ubiquitin ligase, CGRRF1, in breast cancer and identify EGFR as its ubiquitin ligase substrate through unbiased RPPA analysis." (PMID 31801577, 2019).
breast carcinoma (continued). "To study the effect of CGRRF1 on the growth of breast cancer cell lines, we used two shRNAs (shCGRRF1#1 and shCGRRF1#2) to generate stable CGRRF1-knockdown cell lines." (PMID 31801577, 2019). "Kaplan-Meier survival analysis from the van de Vijver database (stages I and II breast cancer) shows that breast cancer patients with low CGRRF1 expression in their breast tumors had poor survival." (PMID 31801577, 2019). "We first examined the expression of CGRRF1 by western blot analysis in a panel of breast cancer cell lines." (PMID 31801577, 2019). "In this study, we demonstrate that CGRRF1 suppresses the growth of breast cancer and the RING-finger domain is involved in its growth-inhibitory activity." (PMID 31801577, 2019). "Supporting this, CGRRF1 expression in these breast cancer cells can be enhanced by treatment with a demethylating agent, 5-azactidine, and an HDAC inhibitor, panobinostat." (PMID 31801577, 2019). "Western blot, subcellular fractionation, and reverse transcription quantitative polymerase chain reaction (qRT-PCR) were performed to understand the mechanism of CGRRF1 action in breast cancer." (PMID 31801577, 2019). "Since 5-azactidine and panobinostat can increase CGRRF1 expression, they might be potential therapies for breast cancer treatment." (PMID 31801577, 2019). "Indeed, 5-azacitidine treatment increased the CGRRF1 transcripts and protein expression in breast cancer cells." (PMID 31801577, 2019). "To further investigate whether CGRRF1 expression bears prognostic significance within the same subtype of breast cancer, we used the KM Plotter server to perform analysis of each subtype from a large number of datasets." (PMID 31801577, 2019). "Since epigenetic change is a reversible process and breast cancer patients with higher CGRRF1 had better survival, increasing the expression of CGRRF1 by altering the epigenetic modification might be a potential therapy that deserves future investigation." (PMID 31801577, 2019). "We also show that CGRRF1 downregulation in breast cancer cells can be reversed by a hypomethylating agent or a histone deacetylase inhibitor, supporting an epigenetic mechanism for its downregulation in breast cancer." (PMID 31801577, 2019). "To investigate whether CGRRF1 inhibits the growth of breast cancer, we performed MTT assays and a xenograft experiment." (PMID 31801577, 2019). "Since knockdown of CGRRF1 enhanced the proliferation of breast cancer cell lines, we generated stable CGRRF1-overexpressing cell lines to study whether overexpression of CGRRF1 could inhibit cell growth." (PMID 31801577, 2019). "As compared to normal breast tissues, the mRNA levels of CGRRF1 are lower in breast carcinomas, especially in HER2-positive and basal-like breast cancers." (PMID 31801577, 2019). "Previous studies suggest a growth repressor function for CGRRF1; however, its role in breast cancer has not been determined." (PMID 31801577, 2019). "Although the sample number is small, there is a very significant negative correlation (r = −0.56) between CGRRF1 and EGFR protein levels in the breast cancer cell lines." (PMID 31801577, 2019).
breast tumors (1 paper, 2019). "To investigate the effect of CGRRF1 on breast tumor growth in vivo, we injected stable CGRRF1-overexpressing MDA-MB-231 cells into NOD scid IL2 receptor γ chain knockout (NSG) female mice." (PMID 31801577, 2019). "Indeed, there is a significant increase in CGRRF1 promoter methylation in breast tumors compared to that in normal breast tissues." (PMID 31801577, 2019).
colon adenocarcinoma (1 paper, 2018). "Notably, CGRRF1 mRNA levels are reduced in several cancers including endometrial and colon adenocarcinomas (Fig EV5G, TCGA)." (PMID 29378775, 2018).
colon carcinoma (1 paper, 2019).
dental caries (1 paper, 2012). The decay of a tooth, in which it becomes softened, discolored, and/or porous. "The association signal is centered over a region of low recombination harboring 4 genes, CDKN3, CNIH, GMFB and CGRRF1 (none of which have known or biologically plausible roles in dental caries)." (PMID 23259602, 2012).
kidney carcinoma (1 paper, 2019). Primary or metastatic malignant neoplasm involving the kidney. "We also found similar results in patients with kidney carcinoma or lung adenocarcinoma, suggesting a general role for CGRRF1 in suppressing tumor growth." (PMID 31801577, 2019).
tumor (4 papers, 2019 to 2025). "Furthermore, several studies reported that the mRNA level of CGRRF1 is downregulated in tumor tissues including testicular germ cell tumor, endometrial tumor, and colorectal cancer." (PMID 31801577, 2019). "This phenomenon may be attributed to gefitinib-induced paradoxical activation of ERK1/2 in resistant cells through the MSI2-AGO2/miR-30a-3p-CGRRF1 regulatory axis, which subsequently activates the KRAS/ERK pathway to promote tumor progression and drug resistance." (PMID 41155547, 2025).
cancer (3 papers, 2018 to 2019). A tumor composed of atypical neoplastic, often pleomorphic cells that invade other tissues. "Other lncRNAs were mainly correlated with either immune-associated pathways, with lnc-CGRRF1-3:1 as an example, or cancer-associated pathways, with lnc-ACSBG2-1:1 and lnc-ANKRD54-1:1 as examples." (PMID 31810243, 2019). "Since EGFR is a driver of tumorigenesis, hyperactivation of EGFR signaling pathways caused by CGRRF1 promoter hypermethylation and downregulation seen in many types of cancer may contribute to cancer progression." (PMID 31801577, 2019). "The expression of CGRRF1 is lower in cancer tissues, most likely due to hypermethylation of the CGRRF1 promoter." (PMID 31801577, 2019). "CGRRF1 expression is lower in estrogen receptor-negative breast cancers than in estrogen receptor-positive cancers (Oncomine)." (PMID 31801577, 2019). "In addition, similar negative correlation between CGRRF1 expression and promoter methylation is found in other types of cancer." (PMID 31801577, 2019).
CGRRF1 also shares sentences with these, for which no sentence is quoted: glioblastoma (1 paper); hepatocellular carcinoma (1); infection (1); lung adenocarcinoma (1); ovarian carcinoma (1).